IL9 (interleukin 9)
Diseases named in the same sentence as IL9 in open-access papers (continued):
Sharing a sentence is not in itself a finding about the gene and the disease.
infection (continued). "In contrast, IL-9 reaches to peak within 3 days and drop quickly when the infection is still increasing." (PMID 25646821, 2015). "We further measured the levels of Cm-specific IgA, IgG1 and IgG2a Abs in the sera collected from IL-9-neutralized and isotype control mice after infection." (PMID 25646821, 2015). "Taken together, these results show that increased production of IL-9 during the first days of infection was central for establishment of enhanced resistance in Treg-depleted BALB/c DEREG mice." (PMID 24516385, 2014). "The numbers of parasitic S. ratti adults in Treg-depleted mice receiving late IL-9 neutralization were significantly lower than parasite burden in Treg-depleted BALB/c mice where IL-9 was neutralized from the beginning of infection." (PMID 24516385, 2014). "We did not observe differential regulation of any other effector relevant for infection control apart from IL-9 production and mast cell activation." (PMID 24516385, 2014). "It would be interesting to investigate the role of IL-9 during pregnancy in infection or inflammation conditions." (PMID 25259859, 2014). "Genetically determined differences in the impact of Treg on immune regulation during infection as well as strain-specific differences in the impact of IL-9-driven and mast cell-mediated intestinal inflammation have been reported in other models." (PMID 24516385, 2014). "Lymphocytes of S. Typhi-infected patients in convalescence stimulated with MP for 48 hours generated significantly higher IFN-γ, MIP-1β, TNF-β, IL-13, and IL-9 responses than lymphocytes of the same patients in the acute phase of infection." (PMID 24615129, 2014). "As Treg depletion also reduced worm burden only if Treg were depleted during the first days of infection, we suggest that Treg control early IL-9 production in BALB/c mice." (PMID 24516385, 2014). "Among these cytokines, levels of IL-9 were significantly increased upon infection and decreased after treatments, showing a positive correlation with level of IL-4." (PMID 24799769, 2014). "IL-9 neutralization throughout infection, achieved by anti-IL-9 injections at the day of infection and at day 3 p.i., abrogated the beneficial effect of Treg depletion in BALB/c mice as expected." (PMID 24516385, 2014). "By neutralizing IL-9 at different time points post infection we further show that IL-9 neutralization in Treg-depleted BALB/c mice later than day 2 p.i. did not restore the susceptible phenotype of BALB/c mice containing normal Treg frequencies." (PMID 24516385, 2014). "Taken together, these findings suggested the possibility that Dengue virus induces VEGF secretion from human mast cells during infection, and that IL-9 supports the production of VEGF in mast cells." (PMID 22363824, 2012). "ratti infection, IL-9-producing CD4+ T cells were proportionally increased." (PMID 41901710, 2026). "IL-9 facilitates helminth Ts expulsion during the enteric phase of infection." (PMID 38727220, 2024). "In the WT re-challenged mice group, these cytokines except IL-9 were significantly high till 30 days post infection and they could be responsible for protective immunity." (PMID 38783167, 2024). "In summary, Sap2‐273L infected mice displayed higher fungal load overall, less C3a release all the time, more exhausted CD4+ T cells, Treg cells and M2 macrophage induced, as well as less pro‐inflammatory cytokines released, but more IL‐10 and IL‐9 production at day 12 post‐infection." (PMID 37211685, 2023). "The Th2-type cytokine IL-9 levels were highest in stable (≤60y) AE patients, slightly lower in progressive AE, older stable (≥60y) and cured AE cases and at similar levels as measured in infection-free controls." (PMID 35108275, 2022). "Since IL-9 is involved in the pathogenesis of various infectious diseases in different organs, we investigated its role in T. cruzi strain Y infection of myoblasts and macrophages, and in a murine model of experimental infection." (PMID 34722343, 2021).
infection (continued). "Some cytokines were observed to be decreased in all infection groups including IL-9, FGF, and PDGF." (PMID 32373548, 2020). "Among 27 cytokine proteins included in this study, 9 cytokines (TNF-α, IL-8, MIP-1α, MIP-1b, MCP-1, RANTES, IL-1rα, IL-9, IP-10) were found at measurable levels in culture supernatants of PHHs following mock infection and/or DENV-2 infection at MOI of 5 for 48 h." (PMID 33216752, 2020). "Interestingly, in contrast to the reduction in IL-4, IL-9 and IL-13 cytokine release later in infection, we saw a stronger, secondary peak of TGFβ at day 12 p.i.." (PMID 30998782, 2019). "ES-polycys was divided into four sub-groups on the basis of hydrodynamic size, and the sub-groups that afforded the greatest protection following vaccination (sub-groups 3 and 4) also induced the greatest IL-13 (and IL-9) secretion by infection-primed MLN lymphocytes." (PMID 29540816, 2018). "In sharp contrast, deficiency of mast cells resulted in prolonged infection to more than 20 weeks pointing out the non-redundant function of IL-9 activated mast cells as intestinal effectors during S. ratti infection." (PMID 30496188, 2018). "As expected, the neutralization of IL-9 clearly reduced fungal burden and restrained inflammation after 3 days of infection as showed by decreased inflammatory cytokine production and neutrophils recruitment at the vaginal parenchyma in absence of epithelial damage." (PMID 30515173, 2018). "Although similar basic clearance of Pneumocystis organisms was achieved in both WT and IL-9−/− PCP mice, IL-9 deficiency could lower Pneumocystis organism burden and promote pulmonary Th17 cells response in the early stage of infection." (PMID 29887863, 2018). "There was very little IL-13 and IL-9 produced by naïve lymphocytes in response to stimulation with these fractions, suggesting that these fractions contain parasite-specific antigens that drive Th2 cytokine release during acute infection." (PMID 29540816, 2018). "V3000 infection uniquely modulated several inflammatory signaling pathways such as IL-2, IL-4, IL-8, IL-9, IL-12 and IL-17A along with the unfolded protein response, gap junction signaling, crosstalk between DCs and NKCs, interferon and JAK/Stat signaling pathways." (PMID 28446152, 2017). "However, the level of IL-9 in liver increased very slowly at 4 weeks post-infection compared to that in spleen." (PMID 28646920, 2017). "To examine the baseline (or steady state) as well as antigen-stimulated production of IL-9 in Ss infections, we cultured whole blood from INF and UN individuals with media alone or with Ss Ag or P/I and measured the levels of IL-9 production in the supernatants at 18 h by ELISA." (PMID 26730582, 2016). "In this work, we analyzed the kinetics of IL-9 production in the lung tissues following intranasal infection with Cm and tested the influence of the endogenous IL-9 production on T cell and B cell responses as well as disease outcomes using in vitro and in vivo antibody neutralization approaches." (PMID 25646821, 2015). "Notably, the kinetics of IL-9 response in this infection model fits that observed in a hen egg lysozyme (HEL) immunization model, showing peaks of IL-9 at day 3 and subsequent sharp decline." (PMID 25646821, 2015). "Since our and others’ previous work has shown a critical role of Th1 and Th17 cells in host defense against chlamydial lung infection, we here examined the role of IL-9 responses in Chlamydia muridarum (Cm) lung infection, particularly its effect on Th1 and Th17 responses and outcome infection." (PMID 25646821, 2015). "This suggests that IL-9 may be involved in AE infection process and may have a potential role in parasite clearance as shown in previous studies." (PMID 26509179, 2015). "Based on literature review of other models and infections, we initially hypothesized that IL-9 plays either a protective or detrimental role in host defense against chlamydial lung infection." (PMID 25646821, 2015).
infection (continued). "Considering the reported effect of IL-9 on Th1/Th17 cells, we examined, in the present study, IL-9 responses following chlamydial lung infection and the influence of this response on adaptive T cell and B cell responses as well as on the outcome of infection." (PMID 25646821, 2015). "The very transient nature of IL-9 production could be one of the reasons for the insignificance of this cytokine in infection." (PMID 25646821, 2015). "More importantly, IL-9 may play a role in secondary infection involving the development and maintenance of immune memory." (PMID 25646821, 2015). "Th9 and IL-9 were involved in Eg infection and might play potentially beneficial roles in the growth of Eg at the late stage after infection." (PMID 24799769, 2014). "Our data suggest that Th9/IL-9 may be involved in regulating the immune response in the infection with Echinococcus." (PMID 24799769, 2014). "The IL-4, IL-5, IL-9, and IL-13 pretreatment responses were subtracted from 1 year posttreatment responses, and correlations between the changes and pretreatment infection intensity, a proxy of the amount of worm-derived antigen exposure upon treatment, were calculated." (PMID 24357629, 2014). "When compared with plasma samples from an independent cohort of healthy individuals, cytokines IP-10, VEGF and PDGF-BB were found to be elevated >20 times over controls during the febrile phase of infection, while IL-4, IL-9, IL-10 and IL-1ra were elevated by 10–20 times over controls." (PMID 23209847, 2012). "By 1 hr post H37Rv-infection there was a significant decrease (P<0.001) in the concentration of the cytokines; Rantes, GM-CSF, Eotaxin IL-13, IL-9 and IL-1b." (PMID 22039457, 2011). "However, the polarized type 2 response (IL-4, IL-5, IL-9, and IL-13) might reduce the severity of infection and contribute to the nematode parasite's eradication." (PMID 39103392, 2024). "Individual overexpression of IL9, the top ranking in our functional selection, markedly reduced cardiac inflammation and injury, concomitant with an increase of anti-inflammatory Th2-cells and a reduction of pro-inflammatory Th17- and Th22-cells at 14 days post-infection." (PMID 35508525, 2022). "IL-9−/− mice were used to study the contribution of IL-9/Th9 function in immune responses against a respiratory fungal infection, and we found that IL-9 was highly likely to have a negative effect on clearance of Pneumocystis organisms in the early stage of infection." (PMID 29887863, 2018). "However, the IL9 mRNA level remained unchanged by infection in both breeds." (PMID 27197554, 2016). "However, the promoting effect of IL-9 on Th1 cells appears infection/disease dependent." (PMID 25646821, 2015). "However, the results of these studies are not in keeping with a prior study, which demonstrated that IL-9-deficient mice on a mixed genetic background (129×C57Bl/6 (F2)) effectively control infection with N. brasiliensis." (PMID 24586147, 2014). "The number of activated T cells (subset 2) increased substantially after infection with upregulation of the IFNG, STAT3, STAT4, IL9, FOXP3, and TGFBR1, TGFBR2 genes." (PMID 40573402, 2025). "IL-10 was significantly increased in CC061 mice after MRSA infection, while IL-1β, IL-4, IL-9, IL-18, IL-23, and IL-27 were significantly increased in CC024 mice after infection." (PMID 39178306, 2024). "Moreover, EgP stimulates the TLR2/MyD88/NF-κB signaling pathway, resulting in the synthesis of α-SMA and Collagen I. The data suggest that infection with E. granulosus may stimulate the production of IL-9 through the activation of the TLR2/MyD88/NF-κB signaling pathway, which is mediated by TLR2." (PMID 39199394, 2024). "The findings indicated elevated levels of IL-9 and TLR2 in patients with CE, with the activation of the signaling pathway significantly increased as the duration of infection progressed." (PMID 39199394, 2024).
infection (continued). "It is noteworthy that the concentrations of IL-9 and IL-17a increased in both IFNAR−/−-BS and C57BL/6J-BS following VSV, NiV and EBOV infections compared to those following mock infection." (PMID 39466030, 2024). "Recent research has demonstrated that infection with E. granulosus leads to a notable upregulation of TLR2 and IL-9 expression." (PMID 39199394, 2024). "In order to assess the expression of ST2 and IL-9 in ILC2s, we infected IL-9 reporter mice (INFER) with N. brasiliensis larvae and analyzed lung and small intestine tissue at 0, 4, 7 and 10 days post-infection." (PMID 35711429, 2022). "At day 7 and 10 post-infection, there were trending increases in the ST2+IL-9+ and ST2-IL-9+ populations, however these differences were not statistically significant." (PMID 35711429, 2022). "In contrast, we observed an increase trend in the double positive population at day 4 post infection, and a significant increase in the ST2- IL-9+ population on day 10 post infection." (PMID 35711429, 2022). "In the lamina propria, both IL-9+ populations are increased, however the ST2- IL-9+ is the most abundant subset induced by the infection." (PMID 35711429, 2022). "We extended the analysis to a large panel of soluble factors identifying other cytokines/chemokines upregulated (IP-10, IL-1ra, MCP-1) or downregulated (IL-9, IL-1β, RANTES, MIP-1β) at the earliest stage of infection in household contacts with a positive swab." (PMID 35967321, 2022). "At 7 days post-infection, we observed an increase in this predominant ST2+ IL-9- population along with trending increases in the double positive ILC2 population, and a slight but significant decrease in the double negative ILC population." (PMID 35711429, 2022). "For instance, serum and plasma from patients with a mild to moderate infection contained significantly greater levels of MCP-3, IL-1α, TNFβ, IL-4, IL-5, IL-6, IL-8, IL-9, and IL-13 compared to serum and plasma from patients that were critically ill." (PMID 34790978, 2021). "Upon exposure to alarmin-like proteins released during tissue damage or infections, lung ILC2 numbers rapidly increase and substantial amounts of the type-2 signature cytokines IL-5, IL-9 and IL-13 and also IL-4 are released." (PMID 34177944, 2021). "In an infection mouse model using Nippostrongylus brasiliensis (N. brasiliensis), ILC2-derived IL-9 was shown to be indispensable for the expulsion of worms, prompting muscle contraction, goblet cell hyperplasia, and mast cell hyperproliferation." (PMID 34759931, 2021). "The first, 5 days of infection showed peak levels of IL-1RA, MCP-1, MIP-1β and TNF-α; the second 5 days had peak levels of GM-CSF, IL-1β, IL-6, IL-8, IL-9, IP-10 and MIP-1α; VEGF peaked at 11–15 days." (PMID 32264832, 2020). "During an infection event, IL-33 activates ILC2 to produce IL-9, and the Th9 cells and IL-9 cytokine production is further amplified by IL-9-activated mast cell-driven ILC2 expansion." (PMID 32676074, 2020). "We infected C57BL/6 or Cftr−/−mice intranasally with A. fumigatus and measured IL-9 production, ILC2 and Th9 cell activation in infection." (PMID 28090087, 2017). "Concomitantly with elevated levels of Th1 indicators (IL-12, IFN-γ and iNOS), primary infections induced increased expression of several Th2 markers (IL-33, TSLP, ArgI and Ym-I) and other cytokines such as IL-9." (PMID 27658962, 2016). "Rapid and more-sustained elevations in IL-1ra, MIP-1α, IL-5, IL-10 and IL-17 levels were followed by IL-1β, IL-2, IL-7, IL-9, IL-12, IL-15, IFN-α2, MIP-1β, FGF-2 and GM-CSF at over 2 months post-infection, and accompanied by the recovery of CD4+ cells." (PMID 27830756, 2016). "Historically, low levels of T cell cytokines (IL-2, IL-3, IL-4, IL-5, IL-9, IL-13) have been observed in fatal human cases of infection with EBOV and in infection of NHPs with MARV." (PMID 26512687, 2015).
infection (continued). "We also found that stimulated peripheral blood mononuclear cells (PBMCs) produced significantly increased levels of a number of cytokines at the convalescent versus acute phase of infection, including IFN-γ, MIP-1β, sCD40L, TNF-β, IL-13, and IL-9." (PMID 24615129, 2014). "IL-9-GFP detection in CD4+ T cells in the lung peaked early and declined during the course of infection, whilst IL-9-GFP+ ILC2s were detectable early and remained present throughout, suggesting a transient window of CD4+-T-cell-derived IL-9 in this model." (PMID 24586147, 2014). "Furthermore, we observed a significant increase in TNFα, IL-1α, IL-2, IL-3, IL-4, IL-9, IL-10, IL-12 (P70), IL-17A, and CCL5 on day 4 post-infection in murine macrophages." (PMID 39038037, 2024). "Lastly, other pro-inflammatory cytokines, such as TNF-α, IL-6, IL-8, and IL-9, exhibited significant upregulation at 1dpi compared to controls, and with no further induction at later time points post infection." (PMID 38459109, 2024). "This design may have allowed for the unexpected finding of systemic IL-9 gene expression and protein production by both LTBI individuals and recipients of ID BCG vaccination in response to in vitro infection with BCG." (PMID 38129388, 2023). "In contrast, greater production of IL-4, IL-13, IL-9, and IL-2 was observed following drug treatment irrespective of infection status, consistent with the observation of increased Th2 populations at the PDTB stage." (PMID 37898618, 2023). "The expression of IL9 and its transcription factor SPI1 in hydatid patients was significantly higher in focal tissue, suggesting the formation of chronic granuloma in hydatid by upregulating the expression of Th9 cells, IL9, and transcription factor SPI1 during infection." (PMID 37593762, 2023). "It is important to note that in the fight against infection by pathogens such as parasites, Th1 (with its primary cytokine, IFN-γ), Th2 (with its main cytokine, IL-4), Th9 (with its main cytokine, IL-9) and Th17 (with its main cytokine, IL-17) immune responses play a vital role." (PMID 35933400, 2022). "However, K1544Δcps-infected eyes had significantly increased quantities of IL9, IL10, IL12-p70, MIG, and MIP-1-gamma compared to K1544-infected and scratch control eyes 24 h after infection (p = 0.037, 0.007, 0.029, 0.037, and 0.036, respectively)." (PMID 35456761, 2022). "In summary, we provide evidence for a non-redundant IL-33-triggered ILC2-, IL-9-, and mast cell-dependent innate pathway facilitating the defense against intestinal helminths during the first week of infection." (PMID 33351862, 2020). "A substantial decrease in IL-6, IL-9, IL-12p40/p70, IL-13, IL-17, IFN-γ, CCL5, SCF, TNF-α, TPO, and vascular endothelial growth factor (VEGF) was observed across days 4 through 7 of NTHi infection." (PMID 31548315, 2019). "In contrast, infection of CD4+ T cells with IRF8-expressing retrovirus enhanced Th9 cell differentiation as demonstrated by increased production of IL-9 mRNA and protein without inducing transdifferentiation." (PMID 29233972, 2017). "FACS results indicated that the peak of IL-9+ Th9 cells in the liver mononuclear cells appeared at the early phase of infection (week 5), except that Th9 cells, CD8+ Tc cells, NKT and γδT cells could secrete IL-9 in this model." (PMID 28539607, 2017). "Peak production of IL-9 was also observed in Rag1−/−, and less in Rag1−/−/Il9R−/−, mice early but not late in infection, a finding suggesting that early IL-9 production is IL-9R-dependent and late is T-cell-dependent." (PMID 28090087, 2017). "A peak production of IL-9 occurred during the first week of the infection in C57BL/6 mice to decline thereafter as opposed to Cftr−/−mice in which levels of IL-9 were sustained throughout the infection." (PMID 28090087, 2017). "Indeed Th2 responses were markedly decreased in cre+ mice and we observed reduced production of IL-9 and IL-13 in in vitro MLN restimulation cultures 35 days post infection." (PMID 28598427, 2017).